NMNAT1 (nicotinamide nucleotide adenylyltransferase 1)
Diseases named in the same sentence as NMNAT1 in open-access papers (continued):
Sharing a sentence is not in itself a finding about the gene and the disease.
pancreatic cancer (3 papers, 2024 to 2025). "High levels of AOX1 are associated with better prognosis of bladder, renal, and pancreatic cancers, whereas high NMNAT1 expression is associated with poor survival in cancer patients with hepatocellular carcinoma." (PMID 38254798, 2024). "Under glucose deprivation, pancreatic cancer cells are more likely to survive when L-lactate increases NMNAT1 lactylation and maintains the nuclear NAD+ salvage pathway." (PMID 39968078, 2025). "Subsequent research on lactate-induced enhancement of nicotinamide mononucleotide adenylyltransferase (NMNAT1) lactylation, which promotes pancreatic cancer cell survival under glucose deprivation, revealed that lysine 128 (K128) of NMNAT1 is a key site for lactylation." (PMID 40057816, 2025).
acute myeloid leukemia (2 papers, 2021 to 2024). Acute myeloid leukemia (AML) is a group of neoplasms arising from precursor cells committed to the myeloid cell-line differentiation. "During the submission of this manuscript, two groups reported the distinct roles of NMNAT1 and NMNAT2 in acute myeloid leukemia and ovarian cancer respectively." (PMID 34919052, 2021).
Glomerular sclerosis (2 papers, 2022). Accumulation of scar tissue within the glomerulus. "Additional studies are required to elucidate that Nmnat1 downregulation can attenuate glomerular sclerosis." (PMID 35962139, 2022). "The inactivation of Twist2 by an endogenous ligand or exogenous substance like NMN might regulate the expression of Nmnat1 and reduce glomerular sclerosis due to PARP1 suppression." (PMID 35962139, 2022). "Furthermore, we found glomerulosclerosis in 20-week-old db/db DN mice and injury in mesangial cells incubated with 24 h HG paralleled decrease in NMNAT1, the NAD+ level, and NAD+/NADH ratio." (PMID 35408818, 2022).
hepatocellular carcinoma (2 papers, 2021 to 2024). A malignant tumor that arises from hepatocytes. "To avoid the effects of LSD1 knockdown on the endogenous NMNAT1 expression, we used the lentiviral system to stably express Flag-tagged NMNAT1 in Hepa1.6 hepatoma cells." (PMID 34314389, 2021).
Infertility (2 papers, 2016 to 2024). "The lack of concordance of the suppression of the lifespan extension and infertility phenotypes in the haf-1(lf);gcIs40 mutants argues that the underlying mechanisms of hypoxia resistance and lifespan extension by Nmnat1 are also distinct." (PMID 26913604, 2016). "We found that supplementing animals with the NAD+ precursor nicotinamide mononucleotide (NMN), or genetic overexpression of the NAD+ biosynthetic enzymes NMNAT1 and NMNAT3, could protect against infertility caused by the drugs doxorubicin and cisplatin." (PMID 39169162, 2024). "As a model for chemotherapy induced infertility we used two chemotherapy agents (doxorubicin and cisplatin), testing three interventions (NMN treatment, NMNAT1-Tg and NMNAT3-Tg overexpression) and using three outcomes for fertility (COC yield, breeding, ovarian histology)." (PMID 39169162, 2024).
lung carcinoma (2 papers, 2023 to 2024). "Consistently, another study detected downregulated NMNAT1 expression in a subset of lung cancer cell lines (14 out of 36 cell lines)." (PMID 38396769, 2024). "This reduction in NMNAT1 expression was suggested to be mediated through a heterozygous deletion of the NMNAT1 locus, which is located in a chromosomal region that is deleted in almost one-fifth of lung cancers (chromosome 1: 9746391-31610219)." (PMID 38396769, 2024). "However, low NMNAT1-expressing lung cancer cell lines are more sensitive to the DNA-damaging agent, doxorubicin, compared to high NMNAT1-expressing lung cancer cell lines." (PMID 38396769, 2024). "Whether doxorubicin treatment differentially affects total NAD+ levels in low vs. high NMNAT1-expressing lung cancer cells has not been investigated." (PMID 38396769, 2024). "Under basal conditions, suppressed NMNAT1 expression levels among lung cancer cell lines have not been accompanied by proportional reductions in NAD+ levels, implying that the other two NMNAT isoforms are arguably the main drivers of total cellular NAD+ levels." (PMID 38396769, 2024).
osteosarcoma (2 papers, 2020 to 2021). A usually aggressive malignant bone-forming mesenchymal neoplasm, predominantly affecting adolescents and young adults. "By screening a small library of FDA-approved drugs, we identified actinomycin D (ActD) as a compound synergizing with NMNAT1 gene inactivation to cause osteosarcoma cell death." (PMID 34445574, 2021). "We report that U-2OS human osteosarcoma cells tolerate the genetic inactivation of the NMNAT1 gene and show increased susceptibility to cisplatin and doxorubicin." (PMID 32392755, 2020). "Cisplatin, one of the drugs most commonly used for the treatment of osteosarcoma, caused a marked elevation in NMNAT1 protein expression in U-2OS cells." (PMID 32392755, 2020). "A key question asked in our study was whether NMNAT1 contributes to the cells’ ability to cope with DNA damage caused by chemotherapeutic agents used in osteosarcoma therapy." (PMID 32392755, 2020). "Therefore, we hypothesized that two major nuclear NAD+-dependent mechanisms underlie the tumor-promoting role of NMNAT1 in ActD-treated osteosarcoma cells: PARP and SIRT activities." (PMID 34445574, 2021). "Once isoform-specific NMNAT1 inhibitors become available, the effects of these inhibitors in both osteosarcomas and other cancer types will be interesting." (PMID 34445574, 2021). "In our current study, we aimed to identify novel pathways synergizing with NMNAT1 in the promotion of osteosarcoma cell survival." (PMID 34445574, 2021). "By inhibiting both PARP1- and SIRT1-dependent cellular pathways, NMNAT1 inhibition can be a promising new tool in osteosarcoma chemotherapy." (PMID 34445574, 2021). "Our previous study proved that NMNAT1 is required for DNA repair and survival of cisplatin and doxorubicin-treated osteosarcoma cells." (PMID 34445574, 2021). "We aimed to understand the mechanism behind the sensitizing effect of NMNAT1 on actinomycin D-treated osteosarcoma cells." (PMID 34445574, 2021). "Wild type (WT) and NMNAT1 KO (KO) U2OS osteosarcoma cell lines were used for testing the cytotoxicity of the drugs in the NMNAT1 KO phenotype." (PMID 34445574, 2021). "In our previous work, we showed that inactivation of the NMNAT1 gene sensitizes osteosarcoma cells to the cytotoxic effects of cisplatin and doxorubicin." (PMID 34445574, 2021). "In cells with high basal levels of ribosomal biogenesis (e.g., NMNAT1 KO osteosarcoma cells), blocking rRNA synthesis (e.g., by ActD) leaves more ribosomal proteins unbound and able to interact with MDM2." (PMID 34445574, 2021). "Our screen of 774 FDA-approved drugs identified nine compounds that showed an increased toxicity in the genetically edited U2OS osteosarcoma cells, which lack NMNAT1, compared to their wild type counterparts." (PMID 34445574, 2021). "Genetic inactivation of NMNAT1 sensitizes U-2OS osteosarcoma cells to cisplatin, doxorubicin, or a combination of these two treatments." (PMID 32392755, 2020). "In summary, our work provides the first evidence that NMNAT1 is a promising therapeutic target for osteosarcoma and possibly other tumors as well." (PMID 32392755, 2020). "U-2OS osteosarcoma cells which showed average levels of NMNAT1 expression were chosen for further investigation." (PMID 32392755, 2020). "In the present study, we have investigated the role of NMNAT1 as a potential target in osteosarcoma." (PMID 32392755, 2020). "Compared to the other assayed cell lines, U-2OS osteosarcoma cells displayed an average level of NMNAT1 mRNA." (PMID 32392755, 2020). "In summary, our data identify NMNAT1 as a survival factor in ActD-treated osteosarcoma cells." (PMID 34445574, 2021). "Our results suggest that NMNAT1 inhibition and ActD may represent a novel therapeutic modality for the treatment of osteosarcoma." (PMID 34445574, 2021). "Based on our results, NMNAT1 acts as a survival factor in ActD-treated osteosarcoma cells." (PMID 34445574, 2021).
osteosarcoma (continued). "In our current study, we aimed to investigate whether NMNAT1 plays a role in maintaining cell viability and whether it contributes to osteosarcoma cell survival following genotoxic stimuli." (PMID 32392755, 2020). "Moreover, genetic inactivation of NMNAT1 sensitizes U-2OS osteosarcoma cells to cisplatin, doxorubicin, or a combination of these two treatments." (PMID 32392755, 2020). "An important question raised by our study is whether the anticancer potential of NMNAT1 targeting is restricted to osteosarcoma." (PMID 32392755, 2020). "In summary, NMNAT1 has been identified as a possible target for the treatment of osteosarcoma." (PMID 32392755, 2020). "U-2OS cells unable to respond sufficiently to cisplatin treatment undergo caspase-mediated apoptotic and caspase-independent necroptotic death, suggesting that NMNAT1 may be worth investigating further as a potential target in cancer therapy with special regard to osteosarcoma treatment." (PMID 32392755, 2020). "Our previous results suggest that NMNAT1, a key enzyme in nuclear NAD+ synthesis, facilitates the survival of cisplatin-treated osteosarcoma cells." (PMID 34445574, 2021). "Up to date NMNAT1 mRNA expression levels for osteosarcoma cells (U-2OS, SAOS-2) were not available." (PMID 32392755, 2020).
pancreatic adenocarcinoma (2 papers, 2024 to 2025). "Lactylation of NMNAT1 sustains the nuclear NAD+ salvage pathway, promoting the survival of pancreatic adenocarcinoma cells." (PMID 39325940, 2024). "In pancreatic adenocarcinoma (PAAD), nicotinamide mononucleotide adenylyltransferase 1 (NMNAT1) is modified by Kla, enhancing its nuclear localization and enzymatic activity, thereby supporting the nuclear NAD+ salvage pathway and facilitating cancer progression." (PMID 41285721, 2025).
age (1 paper, 2025). A temporal measurement of the time period elapsed since an identifiable point in the life cycle of an organism. "Supporting this, NMNAT1 overexpression restored NAD+ levels and significantly protected against age‐related cartilage degeneration." (PMID 41194652, 2025).
amyloid (1 paper, 2022). "As Nmnat1 is a predominantly nuclear-localized enzyme, it is unlikely for Nmnat1 to directly interact with APP or amyloid plaques." (PMID 35401143, 2022).
Astigmatism (1 paper, 2020). A type of refraction error associated with abnormal curvatures on the anterior and/or posterior surface of the cornea.
Atrophy (1 paper, 2024). Any weakening or degeneration, especially through lack of use. "The youngest subject displayed the typical NMNAT1-associated central pseudocoloboma and peripheral atrophy at the fundus, while a bilateral cataract impeded fundus examination in the elder individual." (PMID 38892339, 2024).
brain glioma (1 paper, 2021). A malignant glioma that involves the brain. "These brain glioma patient data set results indicate the strong correlation between high NMNAT1 expression with lower survival and poorer clinical outcome." (PMID 34919052, 2021).
chorioretinal disease (1 paper, 2018). "Mice with mutated Nmnat1 can be found in the chemical mutagenesis mouse pool and it has been shown that mice with a homozygous Nmnat1 mutation develop a rapidly progressing chorioretinal disease that begins with photoreceptor degeneration." (PMID 30166529, 2018).
endometriosis (1 paper, 2021). The growth of functional endometrial tissue in anatomic sites outside the uterine body. "Our study suggested that ProEGCG binds to NMNAT1 and NMNAT3 molecules in human endometrial stromal cells and validated in endometriosis mouse model." (PMID 34721014, 2021). "Resveratrol, a polyphenol and a potentially effective therapeutics option for endometriosis, was found as a SIRT1 activator through upregulating NMNAT1 to increase NAD+." (PMID 34721014, 2021). "Endometriosis mice model was successfully developed to study the therapeutics effects of EGCG and ProEGCG, and the interaction involved in NMNAT1 and NMNAT3 PPI network, as enriched by Strings." (PMID 34721014, 2021). "NMNAT1 and NMNAT3 had expressions in the endometrial stromal cells, were genes that undergo transcription in endometriosis and had the most negative Gibbs free energy, denoting the most substantial binding with ProEGCG (NMNAT1: −8.7 kJ/mol; NMNAT3: −10 kJ/mol)." (PMID 34721014, 2021).
Hepatic steatosis (1 paper, 2025). Steatosis is a term used to denote lipid accumulation within hepatocytes. "Multiomics were used in this study to explore the mechanism through which Nmnat1-LKO aggravated hepatic steatosis in ALD." (PMID 40577472, 2025). "Hepatic NMNAT1 null mice exacerbated alcohol-induced hepatic steatosis and liver injury by inhibiting the cysteine sulfinic acid decarboxylase (CSAD)–regulated taurine pathway in a NAD+-dependent manner." (PMID 40577472, 2025). "Meanwhile, Nmnat1-LKO–aggravated hepatic steatosis and liver injury in the presence of alcohol intervention were robustly rescued by Csad-LOE." (PMID 40577472, 2025). "Replenishment of hepatic NMNAT1, a nuclear NAD+ synthase, is critical for mitigating alcohol-associated fatty liver disease." (PMID 40577472, 2025). "Unlike the role of NMNAT1 in ALD, a recent study reported that Nmnat1-LKO was irrelevant with high-fat diet–induced hepatic steatosis; this might be due to the different roles of NAD+ between alcohol- and non–alcohol-induced fatty livers." (PMID 40577472, 2025). "Considering the results from metabolomics and genomics, we speculated that the taurine metabolic pathway might be mechanistically involved in Nmnat1-LKO–deteriorated hepatic steatosis in ALD." (PMID 40577472, 2025). "Nmnat1-LKO aggravated the alcohol-induced nuclear NAD+ decrease and sensitized hepatic steatosis and liver injury in ALD mice." (PMID 40577472, 2025). "Hepatic NMNAT1 knockout aggravated alcohol-induced hepatic NAD+ decline and further hepatic steatosis and liver injury." (PMID 40577472, 2025).
hypercoagulability (1 paper, 2025). "In conclusion, JHP ameliorates early NONFH by regulating lipid metabolism, improving hypercoagulability, and restoring bone homeostasis through the NMNAT1/NMNAT3/NAMPT/STK11/HMGCR/ACAT1 axis." (PMID 40988117, 2025).
IgA nephropathy (1 paper, 2022). "We also examined intra-renal expression levels of Sirt1, Sirt3, Sirt6, and Nmnat1 in specimens from patients with IgA nephropathy." (PMID 35962139, 2022). "Intra-renal expression levels of Sirt1, Sirt3, Sirt6, and Nmnat1 were evaluated in specimens from 27 patients who were histologically diagnosed with FSGS and IgA nephropathy." (PMID 35962139, 2022).
Insulin resistance (1 paper, 2025). Increased resistance towards insulin, that is, diminished effectiveness of insulin in reducing blood glucose levels. "Similarly, the reduction in NMNAT1 expression, by unbalancing NAD+ homeostasis, causes mitochondrial dysfunction, is associated with insulin resistance, and impairs hepatic insulin signaling and hepatokine expression." (PMID 40724814, 2025). "The hypothesis suggests that inflammation or damage induced by BB-DNA may contribute to mitochondrial dysfunction and insulin resistance through the down-expression of NMNAT1 driven by its gene hypermethylation." (PMID 40724814, 2025).
macular degeneration (1 paper, 2020). Loss of vision in the central portion of the retina (macula), secondary to retinal degeneration. "LCA-type 9, characterized by severe, rapidly progressing macular degeneration with early optic nerves atrophy, were diagnosed in two families that revealed to have potentially pathogenic variants in the NMNAT1 gene." (PMID 33308271, 2020).
Macular dystrophy (1 paper, 2024). Macular dystrophy is a nonspecific term for retinal degeneration, generally confined to the macula, usually presumed of genetic origin. "The NMNAT1:c.-57G>A variant was found in an individual with macular dystrophy that carries in trans an extremely rare missense variant for which in silico predictions (REVEL score = 0.797) support a pathogenic effect." (PMID 38184646, 2024).
neuritis (1 paper, 2013). A neuropathy arising from inflammation of one or more nerves. "Nmnat1 has been reported to protect the axon through NAD-dependent deacetylase sirtuin 1 or local nicotinamide adenine dinucleotide synthesis in neuritis, but Nmnat1 is considerably weaker than WldS." (PMID 23469058, 2013).
ocular hypertension (1 paper, 2017). Abnormally high intraocular pressure. "Targeting NMNAT1 expression to the cytoplasm then inducing ocular hypertension protects RGCs from death." (PMID 28424571, 2017). "Cytoplasmic NMNAT1 upregulation protected RGC somas and axons in models of retinal ischemia and ocular hypertension." (PMID 28424571, 2017).
optic atrophy (1 paper, 2018). A disorder characterized by loss of optic nerve fibers. "Reduced retinal vasculature, optic atrophy, and retinal pigment epithelium were reported, suggesting that photoreceptors are most vulnerable to disruptions in NMNAT1, because they are the first cell type to show signs of disease at 1 month in the mutant mice." (PMID 30166529, 2018).
Parkinson disease (1 paper, 2022). A progressive degenerative disorder of the central nervous system characterized by loss of dopamine producing neurons in the substantia nigra and the presence of Lewy bodies in the substantia nigra and locus coeruleus. "The detected alterations were specific and significant as the expression levels of NMNAT1, NMNAT2 and sterile alpha and TIR motif containing 1 (SARM1) were not significantly different in Parkinson’s disease patients compared to controls." (PMID 35397003, 2022).
pneumococcal infection (1 paper, 2023). Infections with bacteria of the species streptococcus pneumoniae. "We then aimed to confirm the regulation of NAMPT and NMNAT1 upon pneumococcal infection in primary cell culture infection models." (PMID 37783679, 2023).
SHILCA syndrome (1 paper, 2021). "In the present work, we report the first case of a patient presenting SHILCA syndrome due to compound heterozygosity of the Alu-mediated NMNAT1 duplication and a novel splicing mutation." (PMID 33668384, 2021). "Altogether, these findings represent new evidence of the correlation between the previously reported NMNAT1 genomic rearrangement and SHILCA syndrome, and provide novel insights into the healthy and pathogenic expression of this gene." (PMID 33668384, 2021). "In conclusion, to our knowledge, our patient is the first case with SHILCA syndrome caused by the compound heterozygosity of the already reported Alu-mediated NMNAT1 duplication and a novel splicing pathogenic variant." (PMID 33668384, 2021). "Altogether, these findings represent new evidence of the correlation of NMNAT1 and SHILCA syndrome, and provide additional insights into the healthy and pathogenic expression of this gene." (PMID 33668384, 2021).
Stroke (1 paper, 2025). Sudden impairment of blood flow to a part of the brain due to occlusion or rupture of an artery to the brain. "Also, levels of NfL, HAGH, and NMNAT1 were associated when measured at 3 months, but not in the acute stroke phase (p > 0.13 for all, acute phase levels)." (PMID 40316737, 2025).